FASLG (Fas ligand)
Diseases named in the same sentence as FASLG in open-access papers (continued):
Sharing a sentence is not in itself a finding about the gene and the disease.
tumor (continued). "Several of those studies link MMP7 with a disrupted Fas-mediated apoptotic response, and inflammation-related facilitation of tumor growth has been proposed to be caused by MMP7 cleavage of Fas ligand." (PMID 21991341, 2011). "In addition, tumour cells can destroy T lymphocytes, causing their death or attacking them through the expression of Fas ligand (FasL)." (PMID 40725141, 2025). "Also, expression of Fas ligand (FasL) in the tumor vasculature is associated with scarce CD8+ infiltration and a predominance of FoxP3+ regulatory T cells (Tregs)." (PMID 39355307, 2024). "Effector CTLs can exert antigen-driven anti-tumor responses through granule exocytosis mediated by perforin and the granule-associated enzymes (granzymes), through Fas ligand (FasL) induced apoptosis, or indirectly through secreted cytokines such as interferon γ (IFNγ)." (PMID 37582744, 2023). "On the other hand, tumor-associated vascular endothelial cells can express programmed death-ligand 1 (PD-L1) and Fas ligand (FasL), selectively inhibit cytotoxic T cells (CTLs), and promote regulatory T cell (Treg) function to enhance the immunosuppressive TME." (PMID 34294146, 2021). "A positive association between FASLG expression was associated with the neoplasm disease lymph node stage in CCA patients (p = 0.041), where 20% of patients with altered FASLG expression were in the American Joint Committee on Cancer (AJCC) lymph node stage N1." (PMID 34069452, 2021). "Moreover, the VEGF-A and pro-inflammatory cytokines cause Fas ligand (FasL) expression by tumor endothelial cells that gain the capacity to put CD8+ T cells but not T-reg cells to death." (PMID 33585218, 2020). "FASLG (Fas ligand), a core gene involved in lymphocyte apoptosis and T-cell development, was down-regulated, which meant partial loss of self-regulation in tumor immunity." (PMID 33043022, 2020). "Although TILs could be found in clinic HNSCC tumor tissues, the elevated expression of the death-associated domains Fas and Fas ligand (FasL) was also detected, indicating that immune cells in TME might be suppressive and functionally exhausted." (PMID 31416244, 2019). "Fas receptor and Fas Ligand (FasL) system are associated with the suppression of apoptosis, insensitivity to chemotherapy, and with providing immune privilege to a majority of the tumours via the Fas mediated apoptosis of tumour-specific lymphocytes." (PMID 31582940, 2019). "CD8+ TC cells cause tumor cell apoptosis through different mechanisms such as the direct binding of the Fas ligand to the Fas receptor on tumor cell surface, recognition of specific epitopes on the tumor cell surface, the release of pore forming perforin, and by secreting cell lysing granzymes." (PMID 30237863, 2018). "While Fas-ligand and to a much lesser extend TNFα, due to the requirement of protein synthesis or transcription inhibitors, are efficient in killing a variety of tumour cells, these ligands cause significant damage to normal tissues that result in life-threatening toxicities." (PMID 38534365, 2024). "Interestingly, IR associated up-regulation of CD95/Fas on tumor cells improves tumor cell kill by effector CD8+ cytotoxic T lymphocytes (CTLs) that express CD95/Fas ligand and may also play a role in delayed apoptosis associated MC." (PMID 22891162, 2012). "Activating receptors such as DNAX accessory molecule-1 (DNAM-1), NKG2D, NKp46, NKp44 and NKp30 lead NK cells to kill tumor cells by secreting perforin and granzyme B. Fas ligand (FasL) and/or TRAIL are responsible for activating the death receptor pathway." (PMID 39791742, 2025). "Direct tumor toxicity, promoted by the recognition of CD1d-presented lipid antigens, is mediated by perforins, granzyme B, and over-expression of the Fas ligand." (PMID 40002679, 2025).
tumor (continued). "Among them, activated CD8+ T cells differentiate to cytotoxic T cells (CTL), which have antimicrobial as well as anti-tumor effects, e.g., through apoptosis-inducing mechanisms such as perforin and granzyme secretion or Fas-ligand–Fas-receptor interactions." (PMID 40497965, 2025). "NK cells also kill tumors via the death receptor pathway involving Fas ligand (FasL) or TRAIL binding to tumor cell receptors, activating caspase-8-mediated apoptosis." (PMID 41375063, 2025). "CD95L (Fas Ligand (FasL)) is also expressed by some cancer cells as a counterattack mechanism to eliminate tumor-targeting immune cells, particularly cytotoxic T cells." (PMID 41304903, 2025). "The Fas receptor–Fas ligand (Fas–FasL) signaling pathway is a vital modulator of tumor cell apoptosis." (PMID 40104499, 2025). "This upregulation en-hances the sensitivity of tumor cells to Fas ligand (FasL)-mediated apoptosis induced by CTLs and NK cells.These findings provide a novel rationale for combining NO donors with immunotherapy to improve anti-tumor immune responses." (PMID 41036604, 2025). "CD8+ T cells, as the primary effector cells in anti-tumor immune responses, have the ability to directly eliminate tumor cells through signaling pathways involving Fas and Fas ligand (FasL)." (PMID 40959570, 2025). "IFNγ stimulates Fas expression on the tumor cells, rendering them more sensitive to contact‐dependent killing by T‐cells or other cells expressing Fas ligand (FasL)." (PMID 40178291, 2025). "For instance, IL-10-negative B cells exhibit elevated expression of Fas ligand (FasL) and mediate direct tumor cell killing through the Fas-FasL signaling pathway." (PMID 41285707, 2025). "Tumor survival factors such as Fas ligand (FasL) or cytokines like IFN-gamma are directly correlated with tumor-free progression in treated patients." (PMID 40291594, 2025). "Resveratrol induced tumor cell death by modulating different signaling pathways through Fas and Fas-ligand (FasL) levels." (PMID 40141143, 2025). "Forkhead box O (FOXO) proteins, including FOXO1, FOXO3, FOXO4, and FOXO6, function as tumor suppressors by regulating cell cycle arrest, DNA repair, and apoptosis through pathways involving cyclins, Bcl-6, Fas ligand (FasL), and TRAIL." (PMID 40718442, 2025). "VEGF also induces the expression of the Fas ligand (FasL) and PD-1 ligand (PD-L1) on the surface of the tumor endothelial cells, promoting T-cell apoptosis and thus further aggravating T-cell exclusion." (PMID 40649958, 2025). "IgA+ B cell clusters, for instance, inhibit CTL expansion and cytotoxicity through IL-10, PD-L1, and Fas ligand (FASL), promoting tumor growth." (PMID 41285707, 2025). "M1 macrophages possess antitumor properties, and NK cells can induce tumor cell apoptosis by interacting with Fas ligand (FasL) or tumor necrosis factor - related apoptosis - inducing ligand (TRAIL) receptors." (PMID 40746529, 2025). "Neutrophils can further induce tumour cell apoptosis by Fas receptor (FasR)-Fas ligand (FasL) engagement." (PMID 41451221, 2025). "Hydroxytamoxifen is an active metabolite produced from tamoxifen, which has been shown to increase FASL (Fas ligand, a pro-apoptotic factor) expression, leading to reduce in vitro cellular growth and decreased tumor progression in xenograft models." (PMID 40145087, 2025). "Many of these EVs contain Fas Ligand (FasL), which induces apoptosis in activated anti‐tumor immune cells, such as T‐cells, and reduces the activity of NK cells." (PMID 40344389, 2025). "Fas ligand (FasL) expressed on activated γδT cells can bind to Fas (CD95) on tumor cells, triggering caspase-dependent apoptosis of the target cells." (PMID 40226616, 2025). "These engineered T cells can also induce tumor cell death through granzyme B (GzmB) and Fas ligand (FasL) pathways." (PMID 40006624, 2025).
tumor (continued). "For instance, miR-21 is one of the key miRNAs that regulate FASLG expression and plays a role in promoting tumor cell invasiveness and proliferation, particularly in cancer." (PMID 40971385, 2025). "For example, it can inhibit tumor cell proliferation through the Fas ligand/Fas pathway, it can also activate innate immunity and adaptive immunity to exert anti-tumor effects." (PMID 40131539, 2025). "TDEVs promote immune evasion by transferring immunosuppressive factors, including PD-L1 and Fas ligand, to immune cells, thereby inhibiting their anti-tumor functions." (PMID 40443670, 2025). "Here, we show that ARID1A loss results in a biologically and clinically relevant immune evasive phenotype in FL by rendering tumor cells resistant to FASLG-induced apoptosis." (PMID 39843653, 2025). "NK cells, cytotoxic effectors of innate immunity, eliminate tumor cells via granzyme/perforin-mediated cytotoxicity, Fas ligand (FasL)-induced apoptosis, and IFNγ production, while orchestrating adaptive immune responses." (PMID 40831559, 2025). "Hypoxia-induced expression of VEGFA potentiates the ability of interleukin-10 (IL-10) and prostaglandin-E2 (PGE2) to drive expression of Fas ligand (FasL) on tumor ECs to selectively induce apoptosis of cytotoxic T cells but leave Treg cells unscathed." (PMID 39567756, 2025). "T-cell receptor-mediated antigen-dependent tumor cytotoxicity directly induces cell death by binding to the Fas ligand on the membrane and suppresses tumor proliferation by secreting IFN-γ." (PMID 40357287, 2025). "Activated CTLs employ two primary mechanisms to kill tumor cells: granule exocytosis and Fas ligand (FasL)-mediated apoptosis induction." (PMID 39845973, 2024). "The Fas–Fas ligand (FasL) pathway is a critical apoptotic signaling pathway used by CTLs and NK cells to induce cell death in target tumor cells." (PMID 39483536, 2024). "At the same time, MMPs act as tumor cell anti-apoptotic mechanisms that sustain tumor growth by cleavage of pro-apoptotic signals, such as the Fas ligand." (PMID 39063046, 2024). "Fas ligand (FasL) expressed on cytotoxic T cells plays an important role in the Fas-mediated killing of tumor cells." (PMID 39409988, 2024). "Activated effector γδT, Th1 and Tc1 CD8+ T cells can induce tumor cell death via cytokines or direct cell-cell contact by using cell surface molecule like Fas ligand (FasL)." (PMID 38650948, 2024). "Second, the death factor Fas ligand (FasL) on the surface of CTL binds to the Fas receptor (FasR) on the surface of tumor cells and activates cystatin 8 to initiate apoptosis." (PMID 38270700, 2024). "The FOXO transcription factor family, with tumor-suppressive functions in various cancers, is involved in apoptosis, triggering the expression of death receptor ligands like Fas ligand, TNF apoptosis ligand and Bcl-XL, bNIP3, and Bim from Bcl-2 family members." (PMID 39734333, 2024). "Tumor endothelial cells express Fas ligand (FasL) involved in T cell apoptosis reducing CD8+ T cells in tumors." (PMID 39325128, 2024). "Other members of the TNF superfamily can mediate direct cell death such as TNF-related apoptosis inducing-ligand (TRAIL) and Fas ligand (FasL) by recruiting the death-inducing signaling complex in tumor cells." (PMID 38307835, 2024). "NK cells exert direct cytotoxic effects on tumor cells by releasing granzyme B and perforin and expressing the Fas ligand (FasL/CD95L)." (PMID 38725070, 2024). "The Fas/Fas ligand (FasL) system is a major apoptosis-regulating pathway with a key role in tumor immune surveillance and metastasis." (PMID 39272785, 2024). "Another mechanism involves the Fas/FasL pathway, where the Fas ligand (FasL) on CTLs binds to the Fas receptor on tumor cells, triggering apoptosis." (PMID 39273009, 2024). "There is evidence that Fas ligand (FasL) expressed on the surface of NK cell-derived exosomes is involved in killing Fas + tumor cells." (PMID 38553754, 2024).
tumor (continued). "These cells mediate their anti-tumor effects through perforin and granzyme axis, the Fas and Fas ligand axis, and cytokine release for sensitizing tumor stroma." (PMID 39664380, 2024). "Activated CD8+ T cells destroy tumor cells by releasing perforin and granzymes or by producing Fas ligand (FasL) and tumor necrosis factor-related apoptosis-inducing ligand (TRAIL)." (PMID 38175694, 2024). "CXCL1 causes the recruitment of neutrophils into the tumor niche; these cells express myeloperoxidase (MPO) and Fas ligand (FasL), which inhibits the anti-tumor effect of lymphocytes." (PMID 38673949, 2024). "Alternatively, some tumors express Fas ligand (FasL), which binds to the Fas receptor on the leukocytes attacking the tumor, producing its apoptotic death." (PMID 39594765, 2024). "The Fas/Fas ligand (FasL) system is an apoptosis-regulating pathway that holds a key role in tumor immune surveillance and metastasis." (PMID 39272785, 2024). "When the CTLs recognize the tumor antigens and are activated, they will release perforin and granzyme and initiate Fas ligand-mediated apoptosis to eradicate tumor cells." (PMID 38348027, 2024). "IL-12 and IFN-γ improve the cytotoxic effects of CD8+ T cells, resulting in the generation of perforin and granzyme, coupled with Fas ligand (FasL), which mediate tumor-suppressive effects." (PMID 37663132, 2023). "Equally noteworthy was the expression of Fas ligand (FasL), hinting at a potential mechanism by which these T-cells induce apoptosis in target tumor cells." (PMID 37894816, 2023). "Destruction of tumor cells by cytotoxic molecules, e.g., perforin, granzymes, granulysin and Fas ligand." (PMID 37511431, 2023). "CTLs are key players in the elimination of tumor or pathogen-infected cells via the phagocytic granule (LG) and Fas ligand (FasL) pathways." (PMID 37422501, 2023). "Secondly, TNF-related apoptosis-inducing ligand (TRAIL) and Fas ligand (FasL) expressed by γδ T cells recognize and bind their respective receptors expressed on tumor cells, thus resulting in the induction of apoptosis." (PMID 37508545, 2023). "Activated NK cells are potent cytokine producers and elicit powerful cytotoxic activities to induce tumour cell death via perforin/granzyme-mediated-mechanisms, Fas ligand (FasL) and TNF-related apoptosis-inducing ligand (TRAIL)." (PMID 35364779, 2023). "Compared to control and sham-HIFU groups, the number of Fas ligand+ and perforin+ tumor-infiltrating lymphocytes (TILs) and apoptotic H22 tumor cells were significantly higher (p < 0.001) in the HIFU group." (PMID 37564660, 2023). "Intriguingly, our investigation into gene expression at the protein level has unveiled increased production of granzyme B, IFN-gamma, TNF-alpha, and soluble Fas ligand (sFasL) pin-transduced TCR-like CAR-T cells upon encountering SK-Mel-37 tumor cells." (PMID 37894816, 2023). "Recently, lots of researches proved that lncRNAs and Fas ligand (FasL) are participated in a majority of tumor immune progression." (PMID 36875764, 2023). "They secret cytotoxic molecules such as perforin and granzymes or express apoptosis-inducing ligands, such as TNF-related apoptosis-inducing ligand (TRAIL) and Fas ligand (FasL), to directly kill tumor cells." (PMID 37147740, 2023). "For instance, Salmonella strains have been genetically manipulated to express Fas ligand (FasL) with the aim of delivering this toxic and potential antitumor cytokine to tumor sites for enhanced therapeutic efficacy." (PMID 37381018, 2023). "For example, Fas ligand (FasL) has been reported to be expressed by the tumor cells, MDSCs, and vascular endothelium in many human solid tumors." (PMID 38077386, 2023). "Cytotoxic CD8+ T lymphocytes not only directly kill tumor cells through perforin and granzyme pathways or the Fas/Fas ligand (FasL) pathway but also indirectly eliminate tumor cells by secreting cytokines such as IFN-γ and TNF-α." (PMID 37836576, 2023).
tumor (continued). "Fas ligand (FasL) has been identified on tumor EVs from amultitude of sources and has been reported to induce apoptosis of T cells uponbinding." (PMID 36202098, 2023). "Whilst CD8+ T cells, like Th1 cells, are potent producers of IFNγ, they additionally exert direct cytotoxicity on tumour cells through Fas ligand (FasL) or perforin and granzyme which can be further enhanced in response to IFNγ signalling." (PMID 37455828, 2023). "Tumor-derived exosomes typically contain tumor antigens as well as immunosuppressive proteins such as FasL (Fas ligand)/CD95L, TRAIL (TNF-related apoptosis-inducing ligand)/TNFSF10, and TGF-ß (transforming growth factor ß)." (PMID 37456253, 2023). "Additional evidence suggests that angiogenic factors such as VEGF, PGE2, and IL-10 promote the surface expression of Fas ligand (FasL) on the tumor endothelium, creating an immunosuppressive microenvironment by selective of CD8+ T-cells." (PMID 37887354, 2023). "The important mechanism used by CD8+ T cells to induce their antitumor effect is the expression of Fas ligand (FasL) in the SI within the interaction of tumor with CD8+ T cells." (PMID 37878888, 2023). "After cytotoxic T lymphocytes (CTLs) recognize target cells, binding of Fas ligand to Fas on the tumor cell surface triggers an apoptotic program within tumor cells." (PMID 36242616, 2023). "Manipulation of S. typhi to express either the proapoptotic Fas ligand or CCL21(chemokine with anti- tumor properties) as a delivery vehicle carrying anti- cancer therapeutics has demonstrated primary tumor inhibition." (PMID 38090593, 2023). "Tumor cells can also trigger apoptosis in T-cells which exhibit the Fas receptor by expressing the Fas ligand (FasL, CD95)." (PMID 36675043, 2023). "Activated CTLs mainly kill target cells through granule exocytosis and Fas ligand (FasL)-mediated apoptosis induction, thus achieving tumor clearance." (PMID 37153795, 2023). "As well, reactive brain-stroma-derived plasmin cleaves the Fas ligand (FasL) present on the surface of the astrocytes, facilitating interaction with its receptor, Fas, and consequently inducing apoptosis in the tumor cells." (PMID 37569410, 2023). "Effector B cells kill tumor cells directly in vitro in antigen-specific and Fas ligand-dependent manner." (PMID 35759090, 2022). "By increasing the expression of the apoptosis-inducing molecule FAS Ligand (FASL) at the level of astrocytes and by increasing the number of Treg cells, the tumor employs two different strategies to induce tolerance." (PMID 35954362, 2022). "Second, the interaction of Fas ligand (FasL) on the CD8+ T-cells with the Fas on tumor cells, which is upregulated by irradiation, activates a caspase cascade, leading to apoptosis of tumor cells." (PMID 35805044, 2022). "In vitro experiments have demonstrated that it can be secreted from macrophages in response to Fas ligand that is released from tumor cells." (PMID 35634293, 2022). "Ionizing radiation has also been shown to increase the sensitivity of tumor cells to immune-mediated cytotoxicity via the Fas/Fas ligand (FasL) pathway." (PMID 35740435, 2022). "As tumor suppressors, FoxO proteins increased the expression level of death receptor ligands such as Fas ligand and tumor necrosis factor (TNF) apoptosis ligand, engaged with pro-apoptotic pathways, and blocked cell cycle progression." (PMID 35721149, 2022). "Lastly, the high expression of Fas ligand (FasL) on tumor ECs selectively eliminates effector CD8+ T cells instead of Tregs, which is attributed to the augmented level of cellular FLICE-inhibitory protein (c-FLIP) on Tregs." (PMID 36439137, 2022). "These MMPs promote vascular and tumoral invasion as well as release tumour necrosis factor-alpha (TNF-α) and soluble Fas ligand which inhibits tumour cell apoptosis." (PMID 36045675, 2022).